ENSG00000285779 (novel protein)
Gene: Protein-coding gene on chromosome 1 (153,959,151 to 153,975,887, reverse strand). Ensembl gene ENSG00000285779.
Genetic constraint (gnomAD): Missense variants: 57 observed, 82.78 expected, observed/expected ratio (o/e) 0.69, 90% interval 0.56 to 0.86. Synonymous variants: 39 observed, 28.83 expected, observed/expected ratio (o/e) 1.35, 90% interval 1.05 to 1.75.